PIGK (phosphatidylinositol glycan anchor biosynthesis class K)
Description:
Catalytic subunit of the glycosylphosphatidylinositol-anchor (GPI-anchor) transamidase (GPI-T) complex that catalyzes the formation of the linkage between a proprotein and a GPI-anchor and participates in GPI anchored protein biosynthesis. Recognizes diverse proproteins at a C-terminal signal peptide (CSP) region that lacks consensus sequence and replaces it with a GPI-anchor via a transamidation reaction. Transamidation catalysis reaction follows a two-phase mechanism. In the acyl-enzyme phase, the carbonyl group of the proproteins's omega-site undergoes a nucleophilic attack forming an enzyme-substrate thioester bond. Followed by a general acid catalysis that allows CSP releasing, regenerating the carbonyl, and forming the acyl-enzyme intermediate. In the GPI-anchor attachment phase, the amino group of the GPI-anchor's ethanolamine phosphate, the one on third mannose (EtNP3), mediates a nucleophilic attack on the carbonyl of the acyl-enzyme intermediate, replacing the CSP, allowing GPI-anchor attachment to the omega-residue, therefore forming the product and freeing the enzyme.
Synonyms: hGPI8; PIG-K; GPI8; NEDHCAS
Tractability: Small molecule: a structure with a bound ligand is known. Antibody: UniProt predicts a signal peptide or a membrane-spanning region. PROTAC: ubiquitination databases record sites on it; its protein half-life has been measured.
Target class: Enzyme; Transferase
Gene: Protein-coding gene on chromosome 1 (77,088,987 to 77,219,508, reverse strand). Ensembl gene ENSG00000142892.
Subcellular location: Endoplasmic reticulum membrane
Pathways (Reactome):
Metabolism of proteins: Attachment of GPI anchor to uPAR
Gene Ontology:
Molecular function: GPI-anchor transamidase activity; protein binding; GPI anchor binding; peptidase activity
Biological process: attachment of GPI anchor to protein; GPI anchored protein biosynthesis; GPI anchor biosynthetic process; proteolysis
Cellular component: endoplasmic reticulum membrane; GPI-anchor transamidase complex; membrane
Genetic constraint (gnomAD): Loss-of-function variants: 4 observed, 2.99 expected, observed/expected ratio (o/e) 1.34, 90% interval 0.6 to 1.91. That is too few expected variants to judge how well the gene tolerates losing a copy. Missense variants: 102 observed, 83.18 expected, observed/expected ratio (o/e) 1.23, 90% interval 1.04 to 1.45. Synonymous variants: 39 observed, 33.87 expected, observed/expected ratio (o/e) 1.15, 90% interval 0.89 to 1.5.
Homologues: Orthologues: chimpanzee PIGK (99% identical), macaque PIGK (97% identical), guinea pig PIGK (96% identical), pig PIGK (94% identical), dog PIGK (92% identical), rat Pigk (92% identical), mouse Pigk (91% identical), tropical clawed frog pigk (82% identical), zebrafish pigk (78% identical), Drosophila melanogaster PIG-K (51% identical), Caenorhabditis elegans pigk-1 (42% identical). Paralogues in human: LGMN (24% identical).
Diseases named in the same sentence as PIGK in open-access papers:
PIGK is named in the same sentence as 24 diseases in open-access papers, as found by Europe PMC text mining. Sharing a sentence is not in itself a finding about the gene and the disease. The quoted sentences say what the papers report.
breast carcinoma (3 papers, 2013 to 2026). "In cancer, PIGK shows tissue-specific expression changes that are upregulated in ovarian, uterine, and breast cancers but downregulated in bladder, liver, and colorectal cancers." (PMID 41399371, 2026).
colorectal cancer (2 papers, 2022 to 2026). A primary or metastatic malignant neoplasm that affects the colon or rectum. "IHC confirmed low expression of ITGA5 and PIGK in colorectal cancer." (PMID 36405728, 2022).
atherosclerosis (1 paper, 2025). A disease characterized by the build-up of fatty material and calcium deposition in the arterial wall resulting in partial or complete occlusion of the arterial lumen. "The results showed a significant upregulation of migrasome‐associated genes, including TSPAN4, TSPAN7, EOGT, and PIGK, in the model group, further supporting the high expression of migrasomes in atherosclerosis." (PMID 40548932, 2025).
Azoospermia (1 paper, 2022). Absence of any measurable level of sperm,whereby spermatozoa cannot be observed even after centrifugation of the semen pellet. "In non-obstructive azoospermia, the gene ATPase phospholipid transporter 9A (ATP9A) was upregulated, whereas the ring finger and WD repeat domain 3 (RFWD3) and phosphatidylinositol glycan anchor biosynthesis class K (PIGK) were downregulated." (PMID 36293429, 2022).
Cerebellar atrophy (1 paper, 2024). Cerebellar atrophy is defined as a cerebellum with initially normal structures, in a posterior fossa with normal size, which displays enlarged fissures (interfolial spaces) in comparison to the foliae secondary to loss of tissue. "Our mouse model provides initial evidence for the importance of PIGK in Purkinje cell development and proposes Purkinje cell apoptosis as the main pathological mechanism underlying GPIBD22 cerebellar atrophy." (PMID 39521780, 2024). "Biallelic mutations in PIGK cause GPI biosynthesis defect 22 (GPIBD22), characterized with developmental delay, hypotonia, and cerebellar atrophy." (PMID 39521780, 2024). "Among these, biallelic mutations in PIGK can lead to GPIBD22, which is characterized by various neurological symptoms, particularly intellectual disability, hypotonia, epilepsy, and cerebellar atrophy." (PMID 39521780, 2024).
colon cancer (1 paper, 2026). "In colon cancer, a common 3′UTR single-nucleotide polymorphism (rs1048575, C/G or G/G alleles) is associated with reduced PIGK protein expression levels, suggesting post-transcriptional regulatory effects." (PMID 41399371, 2026).
enterovirus infection (1 paper, 2025). "To further characterize the role of PIGS or PIGK during enterovirus infection, we next employed EV71 subgenomic replicon systems (SGRs)." (PMID 41252368, 2025).
hepatocellular carcinoma (1 paper, 2023). A malignant tumor that arises from hepatocytes. "SNP 1048575 was associated with low expression of PIGK in patients with hepatocellular carcinoma." (PMID 37752917, 2023).
Infantile encephalopathy (1 paper, 2024). Encephalopathy with onset in the infantile period. "Lastly, we explored the clinical relevance of our findings by asking whether at least a subset of PIGK disease mutants in patients with neurodevelopmental syndrome or severe infantile encephalopathy are SEL1L–HRD1 ERAD substrates." (PMID 38253565, 2024).
microcephaly (1 paper, 2023). A congenital or acquired developmental disorder in which the circumference of the head is smaller than normal for the person's age and sex. "Microcephaly has its highest prevalence in patients with PIGK and PIGS involvement, while PIGT mutated can be macrocephalic." (PMID 37510348, 2023).
Seizure (1 paper, 2023). A seizure is an intermittent abnormality of nervous system physiology characterized by a transient occurrence of signs and/or symptoms due to abnormal excessive or synchronous neuronal activity in the brain. "Seizures are very common in all the forms described, but they are more frequently controlled by medication in PIGK, GPAA1 and PIGU patients; seizures are often in-tractable, on the other hand, in the case of PIGS or PIGT variants." (PMID 37510348, 2023).
Stroke (1 paper, 2023). Sudden impairment of blood flow to a part of the brain due to occlusion or rupture of an artery to the brain. "Moreover, western blot analysis of the lung tissue from BM‐MSC transferred stroke mice (3d after tMCAO) displayed increased expression of migrasome markers of C3ORF64, PIGK, and PGCP, while the level of exosome markers including HSP70 and HSP90 was stable comparing with the PBS‐injected controls." (PMID 37246283, 2023).
viral infection (1 paper, 2025). "We found that vRNA stability was significantly reduced in PIGS- or PIGK-KO cells, and 4μ8C partially rescued viral infection in PIGS- or PIGK-KO cells." (PMID 41252368, 2025).
cancer (6 papers, 2021 to 2026). A tumor composed of atypical neoplastic, often pleomorphic cells that invade other tissues. "In TCGA transcriptome data visualized using TIMER 2.0, PIGK was found to be aberrantly expressed across multiple cancer types." (PMID 41399371, 2026). "Using the cBioPortal database, we analyzed PIGK genetic alterations across various cancer subtypes in the TCGA PanCancer Atlas Studies dataset." (PMID 41399371, 2026). "Enrichment analysis of co-expressed genes showed involvement in cancer-related biological processes, while protein-level interactors of PIGK were enriched in GPI-anchor biosynthesis and membrane-associated pathways." (PMID 41399371, 2026). "Clinical relevance is validated by immunohistochemistry on tissue microarray, and in vitro assays were conducted to assess PIGK-mediated phenotypes, regulation of Family with sequence similarity 20-member C (FAM20C), taxane response, and cancer-associated fibroblast (CAF) formation." (PMID 41399371, 2026). "The “Molecular Mechanism of Cancer (Z-score = 4.56)” was also among the enriched terms, supporting the notion that PIGK may contribute to tumor progression in HNC by involving multiple cancer-associated signaling and regulatory pathways." (PMID 41399371, 2026). "The investigation of PIGK functions may help understand migrasomes in cancer and provide novel targets for treatment." (PMID 38748047, 2024). "PIGT, PIGU, GPAA1, and PIGS are overexpressed in many cancers, whereas PIGK is downregulated." (PMID 34193731, 2021). "The Hrd1-ERAD system may degrade unassembled PIGK to relieve ER stress in cancer cells." (PMID 34193731, 2021). "The results showed that ITGA5, NDST1, CPQ, ITGB1, PIGK, EOGT, and TSPAN4 had amplifications or deletions in most cancers." (PMID 36405728, 2022). "To assess the potential link between PIGK expression and chemotherapeutic resistance, we analyzed the HNC cell line data from the Cancer Cell Line Encyclopedia (CCLE) and Genomics of Drug Sensitivity in Cancer (GDSC) databases." (PMID 41399371, 2026). "Moreover, MCODE-based clustering revealed that PIGK and FAM20C belong to the same protein-protein interaction module enriched in cancer-related pathways." (PMID 41399371, 2026). "There are three marker proteins (NDST1, PIGK, and EOGT) of migrasome expressed in cancer." (PMID 38748047, 2024).
tumor (5 papers, 2022 to 2026). "Taken together, we found that PIGK mRNA and protein levels were significantly elevated in tumor tissues and were consistently associated with adverse clinical features across independent HNC cohorts." (PMID 41399371, 2026). "Among these, only PIGK was consistently upregulated in tumor tissues across both datasets, suggesting its potential oncogenic relevance." (PMID 41399371, 2026). "Consistent with the transcriptomic data, PIGK protein expression was significantly higher in tumor tissues (P = 2.4 × 10-2)." (PMID 41399371, 2026). "Single-cell RNA-seq data from the GSE103322 dataset showed that PIGK expression in malignant cells increased with the tumor stage." (PMID 41399371, 2026). "Of these, 56 were significantly correlated with PIGK in TCGA/HNC cohort after adjusting for tumor purity." (PMID 41399371, 2026). "In HNC, PIGK levels were significantly higher in tumor tissues (n = 520) than in normal tissues (n = 44) (P < 1 × 10-3), supported by the TNMplot gene-chip data." (PMID 41399371, 2026). "Analysis of gene expression data from various cancers reveals that migrasome-related genes, particularly the migrasomes marker protein PIGK, show higher expression levels in multiple tumor tissues, with an increase corresponding to tumor progression." (PMID 40443653, 2025). "However, it remains to be determined whether FAM20C-driven mechanisms under ER stress influence GPI-anchoring processes and PIGK function, particularly in the context of tumor biology." (PMID 41399371, 2026). "To validate the transcriptome-based findings, we performed IHC staining of PIGK in a tissue microarray consisting of tumor (n = 100) and normal (n = 12) tissues." (PMID 41399371, 2026). "Given that CAFs are prominent in the tumor stroma of HNC and are known to exert immunosuppressive effects 27-29, we hypothesized that PIGK may be involved in CAF-mediated tumor-promoting processes." (PMID 41399371, 2026). "Although not statistically significant, the high PIGK group also showed trends toward greater tumor thickness (mean: 5.56 mm, P = 8.2 × 10-2)." (PMID 41399371, 2026). "Among the 33 tumors, PIGK expression was significantly up-regulated in 22 tumors, and there was no tumor with significantly down-regulated expression." (PMID 36405728, 2022). "The Human Protein Atlas database also indicates that PIGK is moderately expressed in normal tongue and salivary gland tissues, which are representative anatomical sites in the head and neck region, suggesting that PIGK may not be entirely tumor-specific." (PMID 41399371, 2026).
infection (1 paper, 2025). The state of being infected such as from the introduction of a foreign agent such as serum, vaccine, antigenic substance or organism. "We next employed this CD55/TM molecule to evaluate the role of PIGS or PIGK during Echo7 infection." (PMID 41252368, 2025). "Similar to Echo7, infection of EV71 or CVB5 was significantly inhibited in PIGS- or PIGK-KO cells." (PMID 41252368, 2025). "PIGS- or PIGK-KO cells supplemented with CD55/TM were restored for CD55 expression, however, these cells still showed impaired infection and resistance to Echo7-induced cell death." (PMID 41252368, 2025).
PIGK also shares sentences with these, for which no sentence is quoted: gastric cancer (2 papers); Ataxia (1); bladder cancer (1); COVID-19 (1); developmental delay (1); head and neck cancer (1); liver cancer (1); prostate carcinoma (1).